SIRT1 (sirtuin 1)
Diseases named in the same sentence as SIRT1 in open-access papers (continued):
Sharing a sentence is not in itself a finding about the gene and the disease.
Obesity (continued). "In the present study we found that AT, but not skeletal muscle, SIRT1 expression is decreased in obesity and is positively related to whole-body insulin sensitivity." (PMID 29417372, 2018). "Given the crucial role of SIRT1 in obesity, it is no surprise that emerging evidence suggests SIRT1 within the brain controls the systematic regulation of glucose/insulin homeostasis." (PMID 30532738, 2018). "SIRT1 activator resveratrol promotes PGC-1α activity and increases the number of mitochondria in muscle cells, which improves mitochondrial function and protects mice against diet-induced obesity and insulin resistance." (PMID 30574122, 2018). "In addition, adipocyte-specific SIRT1 knockout promoted PPAPγ activity and insulin sensitivity under chronic-HFD conditions and obesity." (PMID 29050301, 2017). "There are substantial data to support that increased sirtuin 1 activity counters obesity, the metabolic syndrome, and T2D with or without obesity making it a desirable therapeutic target." (PMID 29163354, 2017). "We suggest the manipulation of the SIRT1 activity and its potentially-coupled regulation of UCP1 could be a possible future drug target in anti-obesity treatment." (PMID 28481291, 2017). "It was demonstrated that SIRT1, an NAD+ dependent type III deacetylase sirtuin, potentiates BAT function enhancing glucose tolerance and inducing resistance to obesity." (PMID 27303302, 2016). "Taken together, substantial data support that increased SIRT1 activity counters obesity, metabolic syndrome, and diabetes with or without obesity." (PMID 26904696, 2016). "Interestingly, in mice, both obesity and aging promote SIRT1 binding to DBC1, leading to a decrease in SIRT1 activity." (PMID 26788256, 2016). "In keeping with this, the Sirt1 agonists, resveratrol or SRT1720, exert protective effects on ovarian follicle numbers and oocyte integrity under detrimental conditions induced by aging, obesity and methylglyoxal-induced oxidative damage." (PMID 25938585, 2015). "Elucidating the exact mechanism by which an HFHS diet and ageing decrease ARC SIRT1 protein and, possibly, NAD biosynthesis may motivate the development of new therapeutics to treat diet-induced obesity and to preserve energy homeostasis during ageing." (PMID 24374551, 2014). "For example, both compounds largely prevented HFD-induced obesity, an effect never observed in SIRT1 transgenic mice." (PMID 24567900, 2014). "In contrast, obesity and HFD reduce SIRT1 and SIRT3 activity in vivo." (PMID 24073959, 2013). "By analogy, activation of SIRT1 by a specific SIRT1 activator called SRT1720 shows preventive effects in metabolic disorders induced by a high calorie intake such as increased insulin sensitivity, increased fat oxidation, and suppressed obesity." (PMID 20976254, 2010). "Treatment with resveratrol (a SIRT1 activator) protects mice against diet-induced obesity and insulin resistance (although SIRT1 is not the only target of resveratrol, and has not been shown to be the critical functional target of the drug in these studies)." (PMID 21566744, 2008). "SIRT1, via deacetylation of PGC-1α, activates gluconeogenesis and represses glycolysis in the liver; protects mice against diet-induced obesity and insulin resistance; promotes the activation of mitochondrial fatty acid oxidation genes and regulates cellular oxygen consumption." (PMID 21566744, 2008). "Further protein-level experiments in hippocampal and prefrontal cortex tissues revealed that the SIRT1/PGC1α pathway was significantly downregulated under the influence of obesity, whereas HIIT activated the SIRT1/PGC1 α pathway to ameliorated cognitive dysfunction induced by obesity in rats." (PMID 41140914, 2025).
Obesity (continued). "Tilianin’s regulation of AMPK, PPARα, PPARγ, SIRT1, gut microbiota, BAT activity, glycogen synthesis, and inflammatory signaling underscores its potential as a multi-target therapeutic agent for metabolic disorders such as obesity, insulin resistance, type 2 diabetes, and MAFLD." (PMID 41254699, 2025). "However, so far, these canonical metabolic pathways in dendritic cells (DCs) were not correlated with SIRT1 in obesity." (PMID 39424786, 2024). "Interestingly, SIRT1 levels in LDs were significantly higher than those measured in both normal weight and obesity (p < 0.05), while they were not different when compared to anorexia (p = 0.2)." (PMID 38732001, 2024). "In our previous work, we showed that nutritional overload in obesity may enhance the expandability of VAT, specifically over SAT, which may occur via downregulation of expression of the histone deacetylases sirtuin 1 (SIRT1) and sirtuin 2 (SIRT2) in the resident adipose staminal cells (ASCs)." (PMID 35806353, 2022). "Additionally, in mice, resveratrol appears to be able to prevent metabolic diseases (such as insulin resistance and obesity) by improving mitochondrial function through the activation of genes such as PGC-1α and SIRT-1; this result was later corroborated in another very similar study." (PMID 36670880, 2022). "Therefore, it can be suggested that the molecules that activate SIRT1 and SIRT2, or inhibit SIRT7, may be a therapeutic strategy for the treatment of obesity." (PMID 35055159, 2022). "Taken together, this study suggests that FGF19 protects skeletal muscle against obesity‐induced muscle atrophy, metabolic derangement and abnormal irisin secretion partially through the AMPK/SIRT‐1/PGC‐α signalling pathway, which might be a potential therapeutic target for obesity and SO." (PMID 33751819, 2021). "Therefore, we hypothesized that obesity in patients with schizophrenia may also be influenced by APOE E4 and SIRT1 genes, but these conclusions need to be verified in future studies." (PMID 34285334, 2021). "For example, mice lacking SIRT1 are hypersensitive to dietary obesity." (PMID 33668705, 2021). "Furthermore, SIRT1, a class-III histone deacetylase with an essential role in inflammation and metabolic homeostasis, has been identified to be regulated by miRNAs in the adipose tissue of individuals with obesity." (PMID 34068765, 2021). "Investigating the metabolic impact of the functional interaction of SIRT1 with SREBF1c and PPARα and insights into how NAD+ metabolism modulates adipocyte function could potentially lead to new avenues in developing therapeutics for obesity complications." (PMID 33854178, 2021). "Although the main source of circulating SIRT1 is not known research results indicate that the negative metabolic effects of obesity could be related, at least in part, to the reduced levels of SIRT1 in the blood." (PMID 32586268, 2020). "Taking into account the functions of SIRT1 as both an inducer of adipogenesis in human visceral APC and a repressor of inflammatory pathways, its downregulation fosters VAT expansion and heightens the inflammatory state of AT in obesity, contributing to IR development." (PMID 32358737, 2020). "The positive relationships of SIRT1 with adiponectin and the negative relationship with leptin were congruent with both fat amount and distribution in all the categories of fat abundance tested, from AN through NW to obesity." (PMID 33202604, 2020). "In addition, other factors that are altered in obesity like LDH, SIRT-1 expression, oxidative stress markers or immune disorders could also contribute to vascular damage." (PMID 31133882, 2019). "Adenosine monophosphate-activated protein kinase enhances sirtuin 1 by increasing NAD/NADH ratio and decreases adipose tissue macrophage infiltration and inflammation, both have been proposed as key regulators to prevent obesity and obesity-related metabolic dysfunction." (PMID 30881343, 2019).
Obesity (continued). "Although the main source of circulating SIRT1 is not known, these results indicate that the negative metabolic effects of obesity could be related, at least in part, to the reduced levels of SIRT1 in the blood." (PMID 30131769, 2018). "Therefore, it can be expected that in the future activation of SIRT1 and SIRT2 or inhibition of SIRT7 by appropriate miRNA, may be a therapeutic strategy for the treatment of obesity." (PMID 27104517, 2016). "SIRT1, an NAD+ dependent type III deacetylase sirtuin, enhances glucose tolerance by potentiating brown adipose tissue function contributing to energy expenditure and browning of WAT and resistance to dietary obesity, interacts with PPARα and is required to activate PGC-1α." (PMID 26834634, 2015). "Together with previous published work, our data provides better understanding of the molecular control of metabolism by SIRT1 and FOXA2, and therefore may contribute to the development of intervention strategies for metabolic derangements like diabetes or obesity." (PMID 24875183, 2014). "And the female mice without SIRT1 in POMC neuron are more sensitive to diet-induced obesity." (PMID 21738790, 2011). "The anti-obesity effect of the absence of iNOS is probably due to changes in pathways promoting the differentiation of brown fat cells, and changes in genes involved in brown fat function, such as Sirt1, Sirt-3 and Pgc-1α." (PMID 20532036, 2010). "Hence, inadequate activation of Nrf2 by suppressed Sirt1 and BDNF levels, as observed in the present study, may lead to insufficient expression of antioxidants and thus, to low‐level chronic neuroinflammation when HFD/obesity persists." (PMID 39230054, 2024). "However, mice lacking SIRT1 in POMC neurons were prone to obesity upon high-fat feeding." (PMID 24567900, 2014). "On the contrary, mice lacking the SIRT1 gene develop exacerbated hepatic steatosis, increased insulin resistance (IR), ectopic lipid accumulation, and AT inflammation, after HFD-induced obesity, worsening and accelerating the aging process." (PMID 39683558, 2024). "In particular, the absence of deacetylation by SIRT1, SIRT2, and SIRT6 can contribute to obesity and diabetes." (PMID 38892574, 2024). "An intriguing finding was that resveratrol treatment in women with severe obesity increased insulin action and AMPK phosphorylation without changing other components in the AMPK signaling network, such as SIRT1 and PGC1α." (PMID 38324260, 2024). "Although specific knockout of SIRT1 in POMC neurons does not affect feeding behavior, mice lacking SIRT1 in POMC neurons demonstrate hypersensitivity to diet-induced obesity by reduced energy expenditure." (PMID 30416425, 2018). "Sirtuin-1 (SIRT1) is an NAD+-dependent histone or non-histone deacetylase and plays a central role in regulating obesity-related inflammation and metabolic disease in adipocytes." (PMID 29050301, 2017). "The aim of our study is to evaluate SIRT1 derived from SAT and plasma of the same subject in individuals with and without obesity to assess whether plasma measurements may provide clinically significant information." (PMID 42075052, 2026). "Interestingly, Sirtuin 1 (SIRT1), a transcriptional target of TAp63, plays a sex-specific role in POMC neurons to prevent obesity in females but not in males, similar to effects of TAp63." (PMID 33826123, 2022). "As an example, lack of SIRT1-, SIRT2-, and SIRT6-dependent deacetylation and activation of specific adipose gene programs was shown to contribute to the development of metabolic disorders, such as type 2 diabetes and obesity." (PMID 34829720, 2021). "Without metformin, the absence of SIRT1 and mTOR block function of CLOCK and BMAL1 during obesity." (PMID 34356626, 2021). "Altogether, the lack of SIRT1-, SIRT2- and SIRT6-dependent deacetylation and activation of specific adipose gene programs can contribute to the development of metabolic conditions, including obesity and T2D." (PMID 33193730, 2020).
Obesity (continued). "Importantly, the AC5/SIRT1 regulation is unique to AC5, since our data show that AC5 KO is resistant to obesity, but AC6 KO did not affect body weight and SIRT1 expression, and AC3 KO actually induced obesity." (PMID 25945149, 2015). "However, Sirt1 overexpression in these neurons did not protect mice from diet-induced obesity, because an HFHS diet negatively regulated ARC SIRT1 protein levels and hypothalamic NAD+ content." (PMID 24374551, 2014).
diabetes (547 papers, 2008 to 2026). "This case–control study investigates the associations of two SIRT1 promoter polymorphisms, rs12778366 and rs3758391, in patients with type 2 diabetes mellitus (T2DM), gestational diabetes mellitus (GDM), preeclampsia, and healthy controls." (PMID 40869934, 2025). "Clinically, activating SIRT1 has been linked to better vascular health in conditions such as hypertension, atherosclerosis, and diabetes." (PMID 40076724, 2025). "The results suggest that hucMSC‐derived exosomes ameliorate diabetes‐associated muscle atrophy by enhancing SIRT1/FoxO1/3a‐mediated mitochondrial function and that Apt conjugation strengthens the effects of MSC‐EXOs on muscle atrophy." (PMID 39871746, 2025). "The findings highlight the potential of DAPA as a therapeutic agent for managing diabetes-associated atrial arrhythmias through the regulation of SIRT1 expression." (PMID 39636756, 2025). "This decrease in Sirt1 levels has been linked to the development of neuropathic pain, a significant and distressing symptom for many individuals with diabetes." (PMID 40958722, 2025). "Incretin mimetics known as glucagon-like peptide-1 (GLP-1) agonists and dipeptidyl peptidase-4 (DPP-4) inhibitors, both used in diabetes treatment, have been associated with the upregulation of SIRT1." (PMID 39861104, 2025). "Administering 40 mg and 500 mg for 6 months to type 2 diabetes mellitus patients increased Sirtuin-1 (Sirt1) expression which was associated with a decrease in H3K56 acetylation and body fat." (PMID 38645564, 2024). "This polymorphism and other gene variants of the SIRT1 have been studied in other complications of diabetes." (PMID 39474345, 2024). "The dysregulation of cellular processes that involve SIRT1 has been linked to the development of diabetes and its associated complications, highlighting the importance of SIRT1 as a potential therapeutic target for managing the disease." (PMID 37985432, 2024). "The elevated expression level of HMGB1 in diabetic retinas is reported to be repressed by the activation of SIRT1, thereby alleviating the retinal endothelial barrier dysfunction caused by diabetes." (PMID 38438663, 2024). "The current study aimed to investigate the possible influence of SIRT1 gene variants in relation to oxidative stress parameters on the susceptibility to type 2 diabetes mellitus (T2DM) and its microvascular complications." (PMID 39474345, 2024). "SIRT1, which is activated by resveratrol, causes improved cardiac function in animal models of diabetes." (PMID 38256676, 2024). "A decline in the PGC-1α/AMPK/SIRT-1 signaling pathway seems to be the underlying mechanism for reduced mitochondrial biogenesis in diabetes." (PMID 38903985, 2024). "In agreement, roflumilast was showed to abolish doxorubicin-induced inflammation and diabetes-associated cardiac dysfunction by upregulating SIRT1." (PMID 37541971, 2024). "In a cohort of elderly patients with type 2 diabetes mellitus (T2D) and vitamin D deficiency, vitamin D supplementation increased the irisin serum levels, along with Sirt1 levels." (PMID 36835539, 2023). "SIRT1 deficiency can lead to metabolic disorders such as diabetes mellitus, neurodegeneration, and NAFLD." (PMID 37305039, 2023). "The expression of some types of HDACs was markedly upregulated, including type-1, -3, -4, and -8 and sirt-1, -6, and -7, while some were downregulated, such as type-2, -9, and -11, suggesting that diabetes caused epigenetic changes in LSK cells of the BM." (PMID 37311905, 2023). "In diabetes, VSMCs calcification is associated with cellular senescence, oxidative stress, DNA damage and is characterized by decreased expression of sirtuin 1 (SIRT1)." (PMID 35336788, 2022). "In this animal model, diabetes was associated with elevated ROS levels causing retinal cells death, along with reduced SIRT1 concentrations." (PMID 35409409, 2022).